ATR (ATR checkpoint kinase)
Diseases named in the same sentence as ATR in open-access papers (continued):
Sharing a sentence is not in itself a finding about the gene and the disease.
gastric cancer (19 papers, 2018 to 2026). A primary or metastatic malignant neoplasm involving the stomach. "While these features have been associated with increased sensitivity to ATR inhibition in other tumor types, their specific role in gastric cancer remains uncharacterized." (PMID 40869030, 2025). "Indeed, ARID1A-deficient gastric cancer cells have shown pronounced genomic instability and apoptotic cell death following ATR inhibition, both in vitro and in patient-derived organoid models." (PMID 40869030, 2025). "Synthetic lethality between ATR inhibition and ATM deficiency has also been shown previously in gastric cancer cells and other tumors, as cells with loss of ATM rely only on ATR for orchestrating DDR." (PMID 41614897, 2026). "Analysis of the Cancer Genome Atlas (TCGA) database revealed that higher ATR expression correlated with more advanced pathological stages in gastric cancer patients, reinforcing the clinical significance of ATR in disease progression and therapy resistance." (PMID 40869030, 2025). "In one of the first studies, researchers tested VE-821, as a specific ATR inhibitor, to explore its impact on cisplatin’s effectiveness in two gastric cancer cell lines (MKN-45 and AGS)." (PMID 40869030, 2025). "In conclusion, this study demonstrated that VE-821 sensitizes gastric cancer cells to cisplatin by inhibiting the ATR-mediated DDR pathway and reversing cisplatin-induced survival signaling." (PMID 40869030, 2025). "Two other clinical trials will investigate elimusertib (BAY 1895344), another promising ATR inhibitor in gastric cancer." (PMID 40869030, 2025). "A previous report demonstrates that the inhibition of ATR led to S-phase cell cycle arrest in gastric cancer cells." (PMID 39941729, 2025). "PAK6 has been proven to promote homologous recombination, enhancing chemoresistance to oxaliplatin through ATR/CHK1 signalling in gastric cancer." (PMID 39233332, 2024). "Moreover, LINC01612 inhibits gastric cancer cell proliferation, induces apoptosis by binding to ATR and suppressing CHK1 phosphorylation, and enhances oxaliplatin sensitivity." (PMID 41135528, 2025). "In gastric cancer, 37 compounds were examined by constructing a library of patient-derived gastric cancer organoid biospecimens, Some new potent compounds such as Abemaciclib, Napabucasin and ATR inhibitor VE-822 had been identified and showed antitumor effects in clinical trials." (PMID 37576596, 2023). "Consequently, assessing NMD pathway integrity may aid in stratifying gastric cancer patients likely to benefit from ATR-targeted therapies, while simultaneously guiding combination strategies to circumvent resistance." (PMID 40869030, 2025). "This review synthesizes current clinical and preclinical evidence on ATR and CHK1 inhibitors as therapeutic strategies in gastric cancer." (PMID 40869030, 2025). "Western blot analysis indicated that DNA-PKcs, ATR, Phospho-ATR, ATM, Phospho-ATM, γH2AX, and H2AX were upregulated in oxaliplatin-resistant gastric cancer cells, indicating that DNA damage repair response was activated in SGC-7901-R and KATO III-R cells." (PMID 33462197, 2021). "KTM2A was found to have interactions with MEN1, MLL1 complex, ATR, KAT8, SP11, and PAX7 none of which have been implicated in gastric cancer before." (PMID 37287033, 2023).
endometrial cancer (18 papers, 2005 to 2026). Primary or metastatic malignant neoplasm involving the endometrium (mucous membrane that lines the endometrial cavity). "In a previous publication, ATR mutation, often associated with poor prognosis, was identified in approximately 5% of the endometrial cancer cases." (PMID 31805725, 2019). "Mutations in the ATR gene are most frequent in endometrial cancer compared with other tumors." (PMID 37109350, 2023). "The ATR G2375, mutated in endometrial cancer, corresponds to the Mec1 G2279." (PMID 33742106, 2021). "Thus, a functional decline of ATM and ATR was associated with the process of the carcinogenesis or malignancy of endometrial cancer." (PMID 31805725, 2019). "Therefore, ATR mutations can promote endometrial cancer tumorigenesis in the context of MSI, which may be related to tumor invasiveness, and identifying ATR mutation status is helpful for targeted therapy of endometrial cancer." (PMID 37109350, 2023). "Increased expression of the KRAS oncogene is identified in 22–43% of endometrial carcinomas and leads to changes in the expression of ATR and CHEK1 genes, key components of the ATR-CHEK1-WEE1 signaling pathway responsible for DNA replication and repair." (PMID 38669256, 2024). "In ECE cases with recurrences, poorly differentiated (G3) endometrial carcinomas were characterized by downregulated mRNA levels of ATR and pATR protein." (PMID 38669256, 2024). "For ATR, we chose colorectal, breast, and endometrial cancers based on the same criteria (n = 30, 30, and 28, respectively)." (PMID 33742106, 2021). "In this study, we examined the anti-tumor effect of the inhibitors of the ATR-Chk1 or ATM-Chk2 pathway in endometrial cancer cells treated with DXR or CDDP, used as standard chemotherapeutic drugs in endometrial cancer treatment." (PMID 31805725, 2019). "In humans a connection between ATR defects and tumorigenesis has also been suggested, mainly by studies reporting somatic changes in ATR in gastric and endometrial cancers exhibiting microsatellite instability." (PMID 15987455, 2005). "The study with involvement of 475 EC patients showed that ATR mutation was specific for microsatellite instability EC subgroup and are associated with high-grade endometrial cancers, without confirmed correlation with overall survival." (PMID 38669256, 2024). "This may offer new opportunities for endometrial cancer treatment with the assessment of EZH2 inhibitors or ATR inhibitors in the setting of recurrent uterine CCC." (PMID 37353806, 2023). "Moreover, the combination of ATR and Chk1 inhibitors induced DNA damage in endometrial cancer cells and inhibited cell proliferation synergistically." (PMID 31805725, 2019). "Moreover, the combination of the ATR and Chk1 inhibitors induced DNA damage in endometrial cancer cells and inhibited cell proliferation synergistically." (PMID 31805725, 2019). "Additionally, we performed a cell viability assay to examine the effect of the ATR inhibitor and a Chk1 inhibitor in endometrial cancer cells." (PMID 31805725, 2019). "Therefore, we believed that the combination of the ATR inhibitor and the Chk1 inhibitor induced DNA damage in endometrial cancer cells." (PMID 31805725, 2019). "The results showed that ATR and BRCA1 were frequently mutated in endometrial cancer patients." (PMID 24346708, 2014).
endometrial cancer (continued). "In vitro and in vivo studies have reported sensitivity of UCS cell lines to the ATR inhibitor elimusertib, and a separate study has reported synergy between Wee1 and ATR inhibition in CCNE1-amplified ovarian and endometrial cancer models." (PMID 40678577, 2025). "In endometrial cancer patients, the expression of ABCG, ATR, CLU, and LRG1 was upregulated, while the expression of SERPINA1 and KNG1 was downregulated." (PMID 39194522, 2024). "In this study, we found significantly elevated mRNA expression levels of the oncoprotein KRAS, along with two replicative stress markers, ATR and CHEK1, in samples of endometrial carcinomas of endometrium (ECE) from patients with relapse." (PMID 38669256, 2024). "The combined indexes in HEC-1-B and HEC-6 endometrial cancer cell lines were 0.43 and 0.28, respectively, suggesting that the co-inhibition of ATR and CHK1 provided excellent antitumor activity in endometrial cancer." (PMID 37109350, 2023). "In this study, we investigated the anti-tumor effect of inhibitors of the ATR-Chk1 and ATM-Chk2 pathways in endometrial cancer cells." (PMID 31805725, 2019). "The results showed that ATR mutations were only observed in endometrial cancers with MSI and were associated with high-grade endometrial cancers, without confirmed correlation with OS or PFS." (PMID 37109350, 2023). "Regarding the effect of ATR inhibitors and ATM inhibitors in endometrial cancer, the ATR inhibitor ETP46464 enhances the anti-tumor effect of CDDP in endometrial cancer cells, but the ATM inhibitor KU55933 does not, while both the inhibitors enhance the effect of irradiation." (PMID 31805725, 2019). "In this study, we investigated the anti-tumor effect of inhibitors of these pathways in vitro by assessing the effect of the combination of ATM or ATR inhibitors and conventional DNA-damaging therapy (doxorubicin (DXR), cisplatin (CDDP), and irradiation) on endometrial cancer cells." (PMID 31805725, 2019). "Several blood-based protein biomarker candidates for endometrial cancer detection were suggested, including the Apolipoprotein family (APOA1/4, APOC1/2/3, and APOE), Clusterin (CLU), Inter-alpha-trypsin inhibitor heavy chain (ITIH2 and ITIH4), and Antithrombin III (ATR/SERPINC1)." (PMID 39194522, 2024). "Recently, it was reported that the combination of an ATR inhibitor and a Chk1 inhibitor induces cancer-specific cell death in breast cancer cells and osteosarcoma cells, but there is no report about its effect on endometrial cancer cells." (PMID 31805725, 2019). "The mRNA expression levels of KRAS, ATR, CHEK1 genes in endometrial cancer tissue samples at stage I with and without recurrence in anamnesis." (PMID 38669256, 2024). "Therefore, in this study, we aimed to clarify the anti-tumor effect of an ATR inhibitor or an ATM inhibitor combined with DXR, CDDP, or irradiation, and if the combination of the ATR inhibitor and the Chk1 inhibitor could induce DNA damage in endometrial cancer cells." (PMID 31805725, 2019). "As for the effect of the ATR inhibitor or the ATM inhibitor in endometrial cancer, a previous report showed that the ATR inhibitor ETP46464 enhanced the effect of CDDP in endometrial cancer cells, but the ATM inhibitor KU55933 did not." (PMID 31805725, 2019).
Telangiectasia (18 papers, 2006 to 2024). Telangiectasias refer to small dilated blood vessels located near the surface of the skin or mucous membranes, measuring between 0.5 and 1 millimeter in diameter. "In this context, the main DDR orchestrators are the members of the PIKK family of kinases, namely, ATM (ataxia telangiectasia mutated), ATR (ataxia telangiectasia and Rad3-related), and DNA-PKCs." (PMID 36091172, 2022). "The second DNA damage reporter Bscl2 is associated with DNA replication and activation of the ATR (ataxia telangiectasia and Rad3-related) DNA damage signalling pathway." (PMID 31935871, 2020). "These patients had elevated expression of ATM (ataxia telangiectasia mutated) and ATR (ataxia telangiectasia and Rad3-related), which are two important kinases involved in tumorigenesis." (PMID 33109073, 2020). "LPLUNC1 also regulates the NPC cell radioresponse by inhibiting VTN-induced activation of the ataxia telangiectasia mutated kinase-Chk2 (ATM-Chk2) and ataxia telangiectasia and Rad3-related kinase-Chk1 (ATR-Chk1) pathways after ionising radiation (IR)." (PMID 30886235, 2019). "When a DSB happened, the histone 2A (H2A)X was rapidly phosphorylated at ser139 by PI3K- like kinase, including ATM (ataxia telangiectasia mutated)/ATR (ataxia telangiectasia and Rad3-related) and DNA-dependent protein kinase." (PMID 27449097, 2016). "This is due to the phosphorylation of DBC1 at Thr454 by the ATM (ataxia telangiectasia-mutated) and ATR (ataxia telangiectasia and Rad3-related) kinases, which create a second binding site for SIRT1." (PMID 24567900, 2014). "The major molecular sensors of DNA damage include ATM (ataxia telangiectasia mutated) and ATR (ataxia telangiectasia and Rad3-related)." (PMID 22957056, 2012). "Berzosertib (formerly M6620, VX-970) is a highly potent and selective, first-in-class inhibitor of ataxia telangiectasia and Rad3-related protein kinase (ATR)." (PMID 34040175, 2021). "The significance of the phosphorylation-dependent Pin1 activity was recently highlighted for isomerization of ATR (ataxia telangiectasia- and Rad3-related)." (PMID 32426354, 2020). "Activation of the DDR stimulates WRN activity, and subsequently, levels decrease over a 12-h period following ATR (ataxia telangiectasia and Rad3 related) phosphorylation; WRN is turned over via the proteasome." (PMID 30890607, 2019). "ATM belongs to the phosphatidylinositol 3-kinase-like protein kinases (PIKK) family, which includes ATR (ataxia telangiectasia and RAD53 related) and DNA-PKCS (catalytic subunit of the DNA-dependent protein kinase), which all participate in DNA damage signaling." (PMID 24651490, 2014).
cervical cancer (15 papers, 2014 to 2025). A primary or metastatic malignant neoplasm involving the cervix. "Correspondingly, our results revealed that miR-107 affected ATR/Chk1 signalling and gene expression, and implicated miR-107 as a therapeutic target in human cervical cancer." (PMID 25386925, 2014). "In cervical cancer models, therapeutic synergy is observed exclusively when ATR inhibition precedes PARP inhibition, as ATR suppression upregulates PARP expression." (PMID 40256842, 2025). "Our study demonstrated that ectopically expressed APOBEC3A caused cell-cycle arrest in the S-phase and downregulated the G2 stage, suggesting that APOBEC3A inhibits the ATR-Chk1 pathway in cervical cancer cells, leading to cell death." (PMID 38021159, 2023). "We used in vitro models of cervical cancer to link these findings to replication stress responses (p-ATR, and ub-PCNA) and expression of HPV16 E7." (PMID 36266721, 2022). "Within our limited panel there was a correlation between ATR and DNA-PKcs protein levels but our analysis of TCGA data indicates a poor correlation in mRNA expression in cervical cancer." (PMID 36077823, 2022). "Kyungsoo Ha c found in cervical cancer that ATR, which is a bona fide heat shock protein (hsp) 90 client protein, is downregulated when hsp90 is inhibited." (PMID 36685972, 2022). "Hsa-miR-107 activated ATR/Chk1 pathway, suppressed cervical cancer invasion and inhibited the tumorigenicity of head and neck squamous cell carcinoma." (PMID 29554896, 2018). "Here we showed that miR-107 directly targeted MCL1 and activated ATR/Chk1 pathway to inhibit proliferation, migration and invasiveness of cervical cancer cells." (PMID 25386925, 2014). "Genes with known or likely deleterious variants among cervical cancer patients with DDR gene alterations were ATM (n = 3, 2.33%), BRCA2 (n = 3, 2.33%), ATR (n = 2, 1.55%), CHEK2 (n = 2, 1.55%), followed by BRCA1 (n = 1, 0.78%), FANCA (n = 1, 0.78%), MSH6 (n = 1, 0.78%), and RAD51D (n = 1, 0.78%)." (PMID 35071000, 2021). "In summary, our data suggest that ATR/Chk1 signaling is a critical component not only for the cellular DNA replication, it also has a major impact on viral DNA amplification and the viability of cervical cancer cell lines." (PMID 31683862, 2019). "It was shown for cervical cancer cells that miR-107 directly targeted MCL1 and activated ATR/Chk1 pathway to inhibit proliferation, migration and invasiveness of cervical cancer cells." (PMID 26033453, 2015).